BDNF (brain derived neurotrophic factor)
Diseases named in the same sentence as BDNF in open-access papers (continued):
Sharing a sentence is not in itself a finding about the gene and the disease.
Anxiety (continued). "The expression of brain-derived neurotrophic factor (BDNF) in the amygdala simultaneously represses both anxiety-like behavior and alcohol consumption." (PMID 33919862, 2021). "Given the essential role of BDNF downregulation in pre-clinical stages of AD and its links to anxiety-like behaviors, we examined BDNF mRNA levels to determine if its cortical expression is altered after generalized immunosuppression." (PMID 33472690, 2021). "We also examined the role of BDNF, since its expression is decreased in the amygdala in models of anxiety while enhanced by anxiolytic interventions." (PMID 33591956, 2021). "BDNF can be highlighted as a mediator of effects of EE on social and anxiety behaviors as well as brain plasticity changes." (PMID 33503967, 2021). "On the other hand, duloxetine activated the BDNF protein expression in brains of rats subjected to the methamphetamine model of anxiety." (PMID 33802323, 2021). "On the one hand, BDNF conditional knockout mice (with reduced BDNF levels in the forebrain) demonstrated increased levels of anxiety and aggression." (PMID 34769417, 2021). "This would be essentially consistent with our findings of a contrasting relationship of serum BDNF with anxiety and depressive symptoms." (PMID 33462179, 2021). "We found that the serum levels of BDNF and T-cell expression of its receptor NGFR were elevated in patients with RA, and decreased serum BDNF levels were correlated with anxiety and biologics used in patients with RA." (PMID 33673283, 2021). "Integrate hippocampus BDNF signal affect the efficacy of antidepressants and the anxiety-like behavior." (PMID 34054732, 2021). "Overexpression of these proteins is associated with an increase in the brain-derived neurotrophic factor (BDNF), which in turn enhances anxiety-related activities." (PMID 34502198, 2021). "We discovered that maternal symptoms of anxiety correlated with significantly raised maternal serum BDNF exclusively in mothers of boys." (PMID 33462179, 2021). "Future studies should address the interaction between these compounds together with BDNF neurotransmitters to better understand the dual roles of H. erinaceus mycelium in both sleep and anxiety." (PMID 34865649, 2021). "Hippocampal BDNF also facilitates anxiolysis, and mice with impaired BDNF/TrkB signaling display increased levels of anxiety." (PMID 31877583, 2020). "Curcumin treatments mitigate the anxiety reaction because of its ability to prevent the neurons through the modification of nitric oxide making and brain-derived neurotrophic factor (BDNF) expression." (PMID 32454872, 2020). "The aim of the present study was to examine the consequences of two models of ELS that differ in terms of their severity on anxiety-like behavior and spatial memory as well as the BDNF levels in the PFC and plasma CORT levels." (PMID 32793001, 2020). "The inverse correlation between salivary BDNF and perceived stress, anxiety and somatic symptoms among the controls are somehow in line with previous observations of decreased plasma/serum BDNF in mood disorders." (PMID 32842964, 2020). "Based on this model, our group used social witnessing stress to stimulate female mice and observed anxiety-like behaviors, which were correlated with decreased BDNF in the hippocampus and mPFC and increased BDNF in the amygdala." (PMID 32085670, 2020). "In a mouse model of chemically induced colitis, B. longum colonization in the gut reduced anxiety-like behavior via activation of the vagal pathway, independently of brain-derived neurotrophic factor production." (PMID 32719681, 2020). "Anxiety-like behavior, decreased locomotion, reduced social interaction, alterations in expression of neuropeptide Y, and Brain Derived Neurotrophic Factor (BDNF) were reported upon DSS treatment in mice." (PMID 32053891, 2020).
Anxiety (continued). "An anxiety-like mood was detected in mice with low BDNF levels infected with the nematode parasite Trichuris muris, but after administration of the probiotic Bifidobacterium longum, the anxious state disappeared and BDNF levels normalized." (PMID 33291597, 2020). "These include studies showing induction of depressive-like behavior following IGF-1 deficiency, decreased depressive- and anxiety-like behavior after chronic FGF-2 treatment, and improved mood function following peripheral BDNF administration." (PMID 33269095, 2020). "Tianeptine improved hippocampal synaptic and memory deficits and anxiety/depression-like behavior in HD mice, possibly through the modulation of BDNF signaling and AMPAR surface diffusion." (PMID 33425919, 2020). "In the present study, QUER treatment significantly reversed the reduction of BDNF mRNA expression by LPS injection, demonstrating that the beneficial effects of QUER can treat anxiety-like behavior by increasing BDNF mRNA expression." (PMID 32419805, 2020). "Previous studies have shown that lower BDNF levels in the brain are closely related to anxiety-like behaviors." (PMID 32850808, 2020). "In this study, germ-free (GF) mice exhibited more anxiety-like behaviors, which were accompanied by higher brain-derived neurotrophic factor (BDNF) levels in the dentate region of the hippocampus." (PMID 32714875, 2020). "The decrease of BDNF expression in the brain, especially in the hippocampus and PFC is associated with anxiety." (PMID 33348565, 2020). "Here, we found a similar trend between alcohol-induced anxiety with systemic and hippocampal BDNF and IL-1β levels." (PMID 32606350, 2020). "Brain-derived neurotrophic factor is the most abundant neurotrophic factor in the brain, and it is related to anxiety and depression." (PMID 33192853, 2020). "BDNF, a member of the neurotrophin family, plays a critical role in the occurrence of mental illnesses, such as depression and anxiety." (PMID 32085670, 2020). "In contrast, decreased BDNF in the hippocampus is implied to participate in social-defeat-induced anxiety-like symptoms." (PMID 32085670, 2020). "For example, neonatal isolation stress can lead to upregulation of miR-124 in the hippocampus of adult rats, accompanied by anxiety-like behaviors, social avoidance, and decreased BDNF levels." (PMID 32085670, 2020). "ASH has an anxiolytic effect against not only mild anxiety, but also anxiety due to higher levels of stress, which is related to an increase in hippocampal brain-derived neurotrophic factor signaling." (PMID 33281485, 2020). "As a result, QUER administration significantly reduced neuroinflammation through the modulation of BDNF and iNOS, thereby improving the anxiety-like symptoms stimulated by LPS injection on the behavioral tests." (PMID 32419805, 2020). "At 60 days of age, rats were subjected to auditory fear conditioning, fear extinction training, and anxiety-like behavior assessments or to anterior cingulate cortex (ACC) brain-derived neurotrophic factor (BDNF) assays." (PMID 31380440, 2019). "Treatment of post-weaned mice with antibiotics was shown to reduce anxiety-like behaviors while promoting cognitive deficits and significantly reducing BDNF levels in the adult brain." (PMID 31749681, 2019). "For example, germ-free mice have reduced anxiety compared to specific pathogen free mice, which is correlated to reduced brain-derived neurotrophic factor (BDNF) expression in the amygdala." (PMID 31749681, 2019). "Future research is required to elucidate the role of BDNF in these specific hypothalamic nuclei regarding anxiety." (PMID 30585393, 2019). "A relationship between development of behavioral disorders, such as anxiety and cognitive deficits, and altered BDNF levels in different CNS regions was demonstrated both in GF mice and in adolescent mice after antibiotic treatment-induced dysbiosis." (PMID 30794676, 2019).
Anxiety (continued). "In summary, early weaning increased anxiety levels by modulating glucocorticoid and BDNF signaling in the PFC." (PMID 30850750, 2019). "We show that continuous exposure to music during the juvenile period not only enhances conditioned fear extinction and reduces anxiety-like behaviors but also increases BDNF levels in the ACC in adult rats after stressful foot shocks." (PMID 31380440, 2019). "BDNF can be decreased in abused children, and chronic stress in rats increases anxiety and depressive-like behaviors, similar to early weaning." (PMID 30850750, 2019). "Collectively, these findings indicate that disruption of mother-infant bonding increases anxiety via modulation of PFC glucocorticoid-BDNF signaling." (PMID 30850750, 2019). "The stimulation of the right DLPFC (group B) significantly increased BDNF in comparison with the sham group (sham tDCS) and decreased anxiety and craving." (PMID 32477481, 2019). "For example, overexpression of brain-derived neurotrophic factor in the BLA leads to enhanced spine density in BLA neurons as well as elevated anxiety-like behaviour, mimicking the effects of stress." (PMID 31193585, 2019). "The improved behavioral performance on spatial memory tasks and anxiety tests after music interventions is likely to be, at least in part, the effect of increased levels of BDNF." (PMID 30618659, 2018). "Another group working with adult (3 months old) mice, demonstrated reduced levels of BDNF in the brain, increased levels of corticosterone, and increased anxiety and depressive-like behavioral after 4 weeks of isolation." (PMID 30214401, 2018). "Our study also found that SPS decreased the expression of BDNF mRNA in rat hippocampus as well as anxiety-like behaviors." (PMID 30460087, 2018). "Previous BDNF Val66Met polymorphism studies in PDM observed a significant main effect of BDNF genotype on anxiety level in PDM group, in which Met/Met PDMs scored higher in anxiety compared with Val-carrier PDMs during menstrual phase." (PMID 30524221, 2018). "Because BDNF has critical roles in anxiety-like symptoms and hippocampal synaptic plasticity, maintenance of BDNF signaling is likely to contribute to the beneficial effects of GPS on anxiety-like symptoms in LPS-injected rats." (PMID 30460112, 2018). "BDNF gene expression decreased in rats under ethanol withdrawal, and BDNF signaling and the dendritic spines are involved in anxiety-like behaviors during ethanol withdrawal in rats." (PMID 29896126, 2018). "Chronic treatment with the studied compound protected corticosterone-treated mice from anhedonic-, depressive-, and anxiety-like behaviors, as well as deceased BDNF and NGF levels in the hippocampus." (PMID 28550529, 2018). "Esculetin ameliorates anxiety and depressive-like behavior by modulating hippocampal BDNF/tropomyosin receptor kinase B (TrkB) signaling, neuroinflammation, and oxidative stress." (PMID 30065945, 2018). "Because BDNF and HCN1 play a key role in ethanol withdrawal-induced anxiety, we performed a western blot analysis of BDNF and HCN1 in the Hip and NAc." (PMID 29896126, 2018). "In the present study, IS exposure increased anxiety-like behaviors, decreased hippocampal BDNF expression, induced hippocampal NF-κB activation, and increased activated microglia/monocytes populations in the hippocampus, particularly the CA3 region." (PMID 30224732, 2018). "Here, BNDF decreased in the NAc and CA1 of the Hip after abstinence from chronic ethanol consumption, suggesting that BDNF is involved in ethanol withdrawal-related anxiety and alcohol-drinking behaviors in rats." (PMID 29896126, 2018). "Preventing decreases in the levels of DA, 5-HT, and BDNF is believed to reduce the prevalence of anxiety and memory deficits." (PMID 30002347, 2018). "These treatments increased blood corticosterone and LPS levels and anxiety-like behaviors, decreased BDNF expression, and induced NF-κB activation and microglia/monocyte populations in the hippocampus." (PMID 30224732, 2018).
Anxiety (continued). "Consistently, social isolation-induced anxiety- and autism-like behaviors are lessened by hippocampal BDNF over-expression." (PMID 29325565, 2018). "Chronic administration of HBK-15 (1.25 mg/kg) and fluoxetine (10 mg/kg) protected corticosterone-treated mice from anhedonic-, depressive-, and anxiety-like behaviors, as well as decreases in BDNF and NGF levels in the hippocampus." (PMID 28550529, 2018). "Chronic treatment with the studied compound protected corticosterone-treated mice from anhedonic-, depressive-, and anxiety-like behaviors, as well as decreases in BDNF and NGF levels in the hippocampus." (PMID 28550529, 2018). "In this context, estradiol replacement has been shown to ameliorate anxiety and depressive behavior along with restoration of hypothalamic BDNF levels in ovariectomized female rats." (PMID 30589890, 2018). "For example, over or under activity-dependent secretion of BDNF will have varying effects on amygdala related behaviors (e.g., fear/anxiety) when compared with cognition (hippocampal-dependent)." (PMID 29867348, 2018). "Specifically, data show that male mice born to germ-free dams have increased hippocampal 5-HT, decreased hippocampal BDNF, altered anxiety, and increased plasma levels of tryptophan." (PMID 28441394, 2017). "The potential significance of age is further highlighted given the suggested role of BDNF rs6265 in the expression of anxiety as a function of gene by environment interaction across development." (PMID 28887539, 2017). "Previous study using a rat model found that opiate exposure compromised memory, increased anxiety levels, and decreased BDNF precursors in the hippocampus." (PMID 29164087, 2017). "Rodent studies implicate BDNF expression in learning and memory, aggressiveness, anxiety-like behavior, and fear memory formation and consolidation." (PMID 28680507, 2017). "Increased anxiety-like behavior was present more often when BDNF expression in the brain was decreased, suggesting a link between BDNF and anxiety symptoms." (PMID 28620285, 2017). "Western blotting assays additionally showed increased expression of CRF1R and BDNF in anxiety-related amygdala." (PMID 27042185, 2016). "The direct role of BDNF in various amygdaloid nuclei in anxiety-like and alcohol drinking behaviors has been well established." (PMID 27303256, 2016). "Microbiota composition has previously been shown to modulate anxiety-like behaviors in adult mice via changes in levels of brain-derived neurotrophic factor in the hippocampus." (PMID 27097105, 2016). "Escitalopram treatment in patients with MNCD-AD or ScVMNCD led to an increase of plasma BDNF concentrations and as a result to a decrease of cognitive, depressive, and anxiety symptom severity." (PMID 27597800, 2016). "We also corroborate in WT mice that EE alters innate anxiety without increasing adult-born cell survival 20 and demonstrate that EE improved anxiety-like behaviour in the 5-HT1AR KO independently of BDNF levels." (PMID 27115125, 2016). "Ethanol increases Bdnf expression, and BDNF signaling pathways in specific brain regions play a profound role in regulating alcohol drinking and anxiety-like behaviors." (PMID 27303256, 2016). "AIE also produces long-lasting reductions in the expression of BDNF in the amygdaloid and hippocampal brain regions of rats during adulthood and these changes are correlated with phenotypes of anxiety and alcohol intake." (PMID 27303256, 2016). "The expression of BDNF protein always decreases in patients with degenerative and vascular dementias, anxiety, affective and behavioral disorders." (PMID 27917343, 2016). "Infusion of BDNF into the hippocampus enhanced water maze reversal learning and reduced anxiety-like behavior in an elevated plus maze, suggesting that hippocampal BDNF improve hippocampal-dependent learning and reduce anxiety." (PMID 26257661, 2015).
Anxiety (continued). "Whereas the inhibition of BDNF expression impairs learning and memory functions, hippocampal BDNF injections improve performances in spatial memory and anxiety tests." (PMID 25814946, 2015). "A causal link has been suggested since conditional deletion of BDNF in the postnatal brain leads to hyperactivity after exposure to stressors, and to higher levels of anxiety-like behavior in the light/dark exploration test." (PMID 25932008, 2015). "We found, that the severity of maternal anxiety was significantly correlated with mean overall methylation of 4 CpG sites located in exon IV of the BDNF promoter region as measured from DNA extracted from mothers’ saliva." (PMID 26649946, 2015). "A case in point is the recent finding of SNPs in the BDNF gene that impair the effectiveness of anxiety treatments." (PMID 27081652, 2015). "Chronic immobilization stress has been shown to induce dendritic hypertrophy in the basolateral nucleus of the amygdala, which appeared to result from an increased expression of BDNF in this structure, and was suggested to be responsible for anxiety behaviour." (PMID 25739024, 2015). "In transgenic mice, overexpression of BDNF has a facilitating effect on anxiety-like behaviour possibly due to increased spine density in amygdale." (PMID 26539329, 2015). "The results of the present study provide a potential link between three anxiety vulnerabilities: BDNF dysfunction, small hippocampal volume and impaired function, and behavioral inhibition." (PMID 26257661, 2015). "It is known that increased circulating glucocorticoids in the wake of excessive, chronic, repetitive stress increases anxiety and impairs Brain-Derived Neurotrophic Factor (BDNF) signaling." (PMID 26649946, 2015). "Recent evidence has indicated that the reduction of BDNF can aggravate anxiety-like behavior in mice." (PMID 26523278, 2015). "It is known that elevated levels of circulating glucocorticoids induced by chronic stress interferes with BDNF signaling and increases anxiety." (PMID 26649946, 2015). "Finally, recent meta-analyses of population-based case control studies on the Val66Met BDNF polymorphism and mental disorders revealed that the Met allele exerts a protective effect for substance-related disorders and results in decreased neuroticism as a vulnerability trait for anxiety." (PMID 24586380, 2014). "We found that NHT has indeed decreased anxiety-like behavior as well as corticosterone levels and increased hippocampus BDNF levels when treated during UCMS." (PMID 24690945, 2014). "Recently, You Chang demonstrated that high alcohol-drinking rats had innately higher anxiety levels, along with less BDNF expression." (PMID 26501066, 2014). "One study with mice overexpressing BDNF in excitatory neurons of the forebrain (HC, cortex, and amygdala) found an antidepressant-like behavioral phenotype with increased anxiety-like behavior." (PMID 24817844, 2014). "We have recently found that treatment of BALB mice previously exposed to stress with the NHT has reduced anxiety-like behavior, normalized the stress response, and increased BDNF levels in the hippocampus." (PMID 24690945, 2014). "When levels of BDNF in the central and medial amygdala were restored to normal, anxiety and alcohol consumption diminished, suggesting that the deficits in BDNF signaling were the key in these disorders." (PMID 26501066, 2014). "During the estrus phase with low estrogen level, BDNF Met/Met homozygous mice exhibited increased anxiety-related behaviors because of decreased BDNF availability and affected BDNF signaling." (PMID 25383981, 2014). "Significant interactions between menstrual cycle and BDNF genotype (F = 7.595, R2 = 0.048, P = 0.007), as well as among menstrual cycle, group and BDNF genotype (F = 4.509, R2 = 0.029, P = 0.035), on the Beck Anxiety Inventory score were noted." (PMID 25383981, 2014).